TUNAR (transmembrane neural differentiation associated intracellular calcium regulator)
Description:
In neurons, plays a role in the regulation of intracellular Ca(2+), possibly by acting as an activator of ATP2A2/SERCA2, thus increasing the efficiency with which Ca(2+) is removed from the cytoplasm (By similarity). Inhibits differentiation of embryonic stem cells into neurons and inhibits neurite outgrowth, likely as a result of its role in intracellular Ca(2+) regulation (By similarity). In pancreatic beta cells, lowers Ca(2+) levels in the endoplasmic reticulum and enhances glucose-stimulated insulin secretion.
Synonyms: pTUNAR; BNLN; TUNA; HI-LNC78; LINC00617
Gene: Protein-coding gene on chromosome 14 (95,866,587 to 95,925,871, forward strand). Ensembl gene ENSG00000250366.
Subcellular location: Endoplasmic reticulum membrane; Extracellular vesicle membrane
Gene Ontology:
Molecular function: ATPase binding
Biological process: endoplasmic reticulum calcium ion homeostasis; positive regulation of insulin secretion involved in cellular response to glucose stimulus; negative regulation of neuron differentiation; neuron projection morphogenesis; regulation of cytosolic calcium ion concentration
Cellular component: endoplasmic reticulum; endoplasmic reticulum membrane
Homologues: Orthologues: guinea pig TUNAR (95% identical), mouse Tunar (95% identical), pig TUNAR (95% identical), chimpanzee TUNAR (72% identical), dog TUNAR (68% identical), rabbit TUNAR (62% identical), tropical clawed frog TUNAR (58% identical).
Diseases named in the same sentence as TUNAR in open-access papers:
TUNAR is named in the same sentence as 6 diseases in open-access papers, as found by Europe PMC text mining. Sharing a sentence is not in itself a finding about the gene and the disease.
TUNAR shares sentences with these, for which no sentence is quoted: breast carcinoma (4 papers); cancer (2); brain tumors (1); glioma (1); teratoma (1); tumor (1).